MRC1 (mannose receptor C-type 1)
Diseases named in the same sentence as MRC1 in open-access papers (continued):
Sharing a sentence is not in itself a finding about the gene and the disease.
tumor (1,652 papers, 2002 to 2026). "Among the M2-like macrophage-derived factors with a known role in tumor progression, Pdgfc and Il10 were upregulated in Mir34a-deficient macrophages, particularly in the Mrc1+ subtype." (PMID 39425000, 2025). "To validate these observations, we analyzed tumor-infiltrating myeloid cells by flow cytometry using CD206 (encoded by Mrc1) and Ly6C to identify tissue macrophages and mo-Mac, respectively." (PMID 41331250, 2025). "The most abundant lesion-resident population was LRM4 which was characterized by expression of Ccl8, Mrc1, Gas6, Marks, Cbr, and Folr2, a signature shared with many tumor-associated macrophages (TAM) (19, –21)." (PMID 39255000, 2024). "Predominantly expressed in dendritic cells and macrophages, MRC1 is implicated in processes such as inflammation, wound healing, and tumor-associated macrophages." (PMID 39216003, 2024). "Cluster 3 expressed monocyte markers such as Plac8 and Ly6c2 while all other clusters highly expressed tumor associated macrophage (TAM) marker Mrc1 and Trem2." (PMID 37954069, 2023). "Tumor-associated macrophages express high levels of MRC1, are considered to contribute to cancer progression, and are closely associated with poor cancer prognosis." (PMID 36845686, 2023). "Compared with what occurred in rGBM, ICB caused prominent T cell infiltration into the tumor parenchyma of BrM, which was associated with the migration of the MRC1+ macrophages from the perivascular space into the tumor bed." (PMID 37655659, 2023). "For example, enforced expression of miR-511-3p, has been shown to suppress tumor formation by downregulating the protumoral gene profile of mannose receptor-1 (MRC1)+ tumor-associated macrophages (TAMs)." (PMID 35886037, 2022). "A detailed analysis of tumor-associated myeloid cells at single-cell resolution suggested that MRC1 is specifically expressed by a TAM subset identified as Macro_C1QC." (PMID 35503656, 2022). "Pearson correlation analysis further showed that OPN was positively associated with M2 macrophage markers (CD163, VSIG4, MS4A4A, CX3CR1, and MRC1) and tumor-associated macrophage (TAM) markers (CCL2, CD68, and IL10)." (PMID 35669197, 2022). "Flow cytometric analysis of tumor-associated immune-cell populations showed an increase in MRC1+ M2-polarized macrophages in the Apoa1 KO background, which was not substantially reverted by reintroduction of APOA1." (PMID 35577388, 2022). "This neutralization led to vascular regression and increased pericyte coverage of the vessels, increased tumor hypoxia, necrosis and enhanced recruitment of MRC1+(CD206) tumor associated macrophages." (PMID 33235291, 2021). "The selective overexpression of the M2‐like macrophage polarization marker Mrc1 let us presuppose an accumulation of tumour‐associated macrophages (TAMs) 48 in NASH‐HCC WT livers." (PMID 32281248, 2020). "10p12.33 was deleted in 79% of the samples and harbored gene MRC1, a M2 macrophage antigen known to be associated with tumor development, invasion, metastasis and angiogenesis." (PMID 32617189, 2020). "For the tumor-associated macrophage populations, this analysis revealed high expression of the alternative activation markers Arg1, Fizz1, and Mrc1, which coincided with reduced mRNA levels of the classically activated marker Nos2." (PMID 31227713, 2019). "The decreased levels of MRC1 and the mast cell markers in the low-stage tumors were a surprising result, because tumor-associated mast cells are reported to be increased in CRC." (PMID 29176937, 2017). "Notably, our research revealed that MVI and its precursor cells have the capacity to recruit MRC1+ tumor-associated macrophages (TAMs) while excluding CD8 T cells." (PMID 39670859, 2025). "Interestingly, miR-511-3p, encoded by MRC1 genes in mouse and humans, decreased pro-tumor activity of MCR1 in MRC+ TAMs and reduced the growth of murine Lewis lung carcinoma (LLC) cells." (PMID 40050933, 2025).
tumor (continued). "In addition, macrophage cluster 3, 8, and 10 associated with tumor progression or metastasis express low levels of Mrc1 (CD206) and high levels of Vegfa, which indicate a phenotype of M2d macrophages facilitating tumor angiogenesis." (PMID 37483625, 2023). "MRC1 is expressed on tumor associated macrophages (TAMs) with M2 phenotype." (PMID 36051466, 2022). "Importantly, CD206 (encoded by Mrc1, M2 marker) expression, among other markers, was increased in tumor-associated macrophages, showing that immune cells acquire a suppressive phenotype in this model." (PMID 32908137, 2020). "ST confirmed Man-Alb enrichment in extracellular matrix (ECM)/TAM-rich clusters (mannose receptor C-type 1, Mrc1-high) and Gal-/Glc-Alb uptake in glycolytic/hypoxic tumor clusters (Slc2a1-high)." (PMID 41355949, 2026). "Clinical sample validation demonstrated that MRC1+ macrophages showed relatively higher rRNA levels than other macrophages did in tumours." (PMID 40646287, 2025). "On the other hand, canine tumor NK cells had increased expression of PTPRC/CD45, a hallmark present on all leukocytes, which had a high probability of interaction with MRC1 on myeloid cells in the canine lung." (PMID 41208961, 2025). "To investigate the main subtype of myeloid cells in the tumor boundary, we compared some classical markers of myeloid subtypes and found that MRC1 had the same expression pattern as CD163." (PMID 39670859, 2025). "In clear cell renal cell carcinoma, IL-1β+ and IL-18+ Tregs co-localize with MRC1+FOLR2+ TAMs at tumor-normal interfaces, forming a positive feedback loop that sustains synergistic pro-tumor effects." (PMID 41417432, 2025). "Then the CXCL5-CXCR2 and LGALS9-HAVCR2 were identified in the cell-cell communication between CXCL5+ SLC6A14+ tumor cells and MRC1+ macrophages." (PMID 39670859, 2025). "Tumor-associated macrophages are known to express the mannose receptor C-type 1 (MRC1, also referred to as CD206) on their surface, a receptor implicated in promoting tumor immunosuppression, angiogenesis, metastasis, and relapse." (PMID 41010517, 2025). "In tumor-associated macrophages (TAMs), OXPHOS and fatty acid oxidation dominate, mediating H3K4me3 modifications via PPARγ to promote anti-inflammatory genes (e.g., ARG1, MRC1) and drive tumor progression." (PMID 40959285, 2025). "In more detail, it was demonstrated that these tumors were characterized by a significant decrease in tumor-supportive MRC1+ cells, an increase in cytotoxic MHCII+ cells, a reduced total number of intratumor Iba1+ myeloid cells, and lower VEGF-A expression." (PMID 39456164, 2024). "All of these subclusters represented M2‐like macrophages marked by the expression of CD163 and MRC1, which potentially contribute to tumour progression." (PMID 38318640, 2024). "Targeting O‐glycosylation by itraconazole successfully suppressed serum IL‐6 levels, upregulated tumor infiltrating CTLs, and downregulated MRC1+ TAMs in vivo." (PMID 37452653, 2024). "The TAM model in the simulated tumor microenvironment was treated with dCP1 and dCPP, respectively, and it was found that glycopeptide can better reduce Mrc1 in M2-like TAM and increase the relative expression levels of IL-1β and IL-6 mRNA." (PMID 38743074, 2024). "By demonstrating that SMLR1 is upregulated in CRLM and interacts with tumor-associated macrophages (TAMs) via MRC1 (CD206) and SIGLEC1 (CD169), this research unveils a novel mechanism of immune evasion and tumor progression." (PMID 39324019, 2024). "A significant elevation of the cytotoxic MHCII+ cell levels was observed along with a reduction in tumor-promoting MRC1+ cells, with a shift to lymphocyte over neutrophil predominance in their blood stream, similarly to Robo receptor-knockdown mice." (PMID 39456164, 2024). "Slit2 treatment further induced gene expression associated with a tumor-promoting macrophage phenotype by activating MMP-9, VEGF-a, Mrc1, Ccl19, TGF-β1, IL-10, Cd209a, and Arg1." (PMID 39456164, 2024).
tumor (continued). "Within the tumor core, the TAMs_0, TAMs_1, TAMs_2, and TAMs_7 subpopulations predominantly expressed M2-like macrophage markers (e.g., MRC1, IL10, and CD163), indicating an inclination towards the M2 phenotype." (PMID 38938448, 2024). "Mac Mrc1-enriched spots were enriched at the tumour periphery, and correlation analysis revealed a significant positive association between Mac Mrc1 and Meg3, Fbln1 and Lrrc15 CAF subtypes, which suggested proximity." (PMID 37605008, 2023). "As expected, the lineage markers CD4, CD8, and CD56 were most abundant in the respective immune cell types, and the macrophage marker MRC1 was highest in liver and tumor macrophages." (PMID 37388918, 2023). "Clusters 1, 5, 11, and 17 all appeared to express significant amounts of CD163 (except cluster 11) and MSR1 (encodes CD204) and variable MRC1 (encodes CD206), classic markers of immunosuppressive/tissue reparative/tumor promoting M2 macrophages." (PMID 36966348, 2023). "Post-mortem histology showed that the number of F4/80+ total TAMs and MRC1+ tumor-supportive TAMs in the TME were decreased by Ccl21a knockdown in GBM, while activated MHC-II+ antigen-presenting cells (APCs) were unchanged." (PMID 37314567, 2023). "M2‐TAMs, known for their elevated MRC1 expression, play a vital role in the advancement of tumours, encompassing tumour expansion, formation of new blood vessels, infiltration and metastasis." (PMID 37784253, 2023). "Results show that C3AR1 has the strongest correlation with M2 macrophages (CD163, MRC1, CD209), tumor-associated macrophages (CCL2, CD86, CD68) and monocyte immune markers, including (CD14, CD33, ITGAX)." (PMID 37005667, 2023). "We identified multiple clusters of mononuclear phagocytes including macrophages (Mac), several of which expressed genes associated with pro-tumour subtypes, including CD206 (Mrc1), Arg1, Retnla, Fn1 and C1qa50,51." (PMID 37605008, 2023). "With respect to the gene expression profile, CCL21 increased the expression of tumor-supportive genes such as Vegfa, Mrc1, Arg1, and Cd274 (PD-L1) in microglia, as well as in BMDMs that also showed increased expression of Il-10 and Tgfβ1." (PMID 37314567, 2023). "Further, MRC1+ macrophages are much more abundant in tumor than in normal tissues, which is consistent with previous studies." (PMID 36902024, 2023). "To investigate the difference between these MRC1+ macrophages residing in the perivascular region and those scattered in the tumor tissue, we identified all BrM spots containing MRC1+ macrophages and looked for DEGs between the 2 regions." (PMID 37655659, 2023). "Immunofluorescence results showed that C1QA expression in tumor, P-LN, and N-LN was higher, while MRC1 in P-LN was higher than that in tumor and N-LN." (PMID 36569924, 2022). "In respective tumor macrophages, Tnfa and Fizz M1 markers were upregulated and the Mrc1 M2 gene was downregulated." (PMID 35315360, 2022). "Crucially both TAM abundance and TME expression of M2-associated TAM genes ARG1, MRC1, and IL10 were reduced, concurrent with an increase in CD8+ T cell tumour infiltration, suggesting a preferential targeting of M2-associated immunosuppressive TAM subsets." (PMID 35020853, 2022). "On the contrary, M2 macrophages express molecules which can be involved in parasite infestation, tissue remodeling and tumor progression such as resistin-like-α, Arginase 1, chitinase-like molecules, IL-10 and mannose receptor C-type 1 (Mrc1)." (PMID 34336660, 2021). "For example, miR-155 expression is low in MRC1+ TAMs and inhibits tumor growth in a breast cancer mouse model by reprogramming M2-like macrophages toward classic M1-like activation." (PMID 34831416, 2021). "The expression of four CAF-specific markers correlated positively with that of CD68, CD163, MRC1, IL10, and TGFB1, which are markers that characterize tumor-associated macrophages (TAMs)." (PMID 33799788, 2021).
tumor (continued). "OLFML2B was highly co-expressed with tumor-associated macrophage markers such as CD14, CD163, CSF1R, ITGAM, and MRC1." (PMID 34868901, 2021). "A correlation of immune cell marker genes, including tumor-associated macrophages (TAMs) (CD209, CD206/MRC1, IL6, IL8, and CXCL10), MDSCs (CD33 and IL6), dendritic cells (DCs) (CD11c/ITGAX, CD209, TNF, and CD80) and Fusobacterium has been found in humans." (PMID 33823861, 2021). "It is known that M2-TAMs are the main tumor-associated anti-inflammatory macrophages with relatively high expression of CD163, MRC1, MS4A4, and MAF." (PMID 33303760, 2020). "In the present study, we designed a probe using Polyamidoamine (PAMAM) fifth-generation (G5) dendrimers conjugated with mannose, Cyanine 7 (Cy7), and hydrazinonicotinamide (HYNIC) for target macrophages with high expression of MRC1 in the tumor." (PMID 33048944, 2020). "MRC1+TIE2HiCXCR4Hi macrophages accumulate and promote tumour revascularization partly via VEGF-A release." (PMID 32541815, 2020). "After being recruited to tumor sites, these macrophages were reshaped into an M2 protumor phenotype (i.e., increased Arg1, Fizz1, and Mrc1 expression) to promote tumor progression." (PMID 32039025, 2019). "Pearson correlation revealed, that Gal3 expressing cells show a significant positive correlation with CD68 positive macrophages and MRC1 positive M2 macrophages in the IFZ of tumor-free cervical lymph nodes." (PMID 30115022, 2018). "In contrast, miR-155 expression is low in MRC1+ TAMs and inhibits tumor growth in a breast cancer mouse model by reprograming M2-like macrophages toward classic M1-like activation." (PMID 29899293, 2018). "In tumor resection specimens, there was a significant positive correlation between Gal3 expressing cells and MRC1 positive macrophages." (PMID 30115022, 2018). "Another strategy involved the enforced expression of miR-511-3p, which is encoded by MRC1 genes, in TAMs, resulting in a decreased protumoral gene signature of MCR1 (MMR)+ TAMs and inhibited murine LLC tumor growth." (PMID 30349530, 2018). "Our sequential in situ labeling of MHCII followed by post‐fixation MRC1 labeling indicates that this progressive stroma alteration comprises a repolarization of M1‐like to M2‐like macrophages within the tumor." (PMID 29038312, 2017). "The opposite was observed in late‐stage tumor growth (5 weeks) where 89% of the macrophages were M2 MHCIIlow MRC1+ macrophages." (PMID 29038312, 2017). "Tumor-associated macrophages (TAMs) expressing the multi-ligand endocytic receptor mannose receptor (CD206/MRC1) contribute to tumor immunosuppression, angiogenesis, metastasis, and relapse." (PMID 29116108, 2017). "In early stages of tumor growth (2 weeks), 72% of the macrophages were MHCIIhigh MRC1neg M1 macrophages and very few MHCIIlow MRC1+ M2 macrophages were detected." (PMID 29038312, 2017). "We performed qPCR analysis of tumor macrophages after specific isolation by magnetic‐activated cell sorting of M1 or M2 macrophages using anti‐MHCII or anti‐MRC1‐coated beads, respectively." (PMID 29038312, 2017). "TAMs showed a M2-like phenotype characterized by expression of Cd206 (Mrc1), Cd163, Pdl2 (Pdcd1lg2), Chi3i3, Arg1, as well as tumour-promoting molecules involved in invasion and metastasis like MMPs." (PMID 27150562, 2016). "Nevertheless, the expression of M2a markers (that is, CD163 (Cd163), mannose receptor complex-1 (Mrc1) and arginase-1 (Arg1) was significantly upregulated in sST2 low-expressing tumours." (PMID 27882929, 2016). "In line with the data obtained in whole tumors, TAMs isolated from B16F10-ARF−/− tumor xenografts exhibited higher expression of typical M2 markers Ym-1 and MRC1 when compared to TAMs from B16F10-WT tumor xenografts." (PMID 27572316, 2016). "IMCs in our model also secrete M2 marker proteins including YM1, arginase-1, MRC1 (soluble CD206) and legumain and promote tumour cell growth in vitro and ex vivo (Fig3)." (PMID 26183450, 2015).
tumor (continued). "For instance, blocking pro-angiogenic factor angiopoitin-2 leads to angiogenesis inhibition and tumor hypoxia, however subsequent enhancement in recruitment of MRC1+ TEMs limits the efficacy of ANG-2 blockade." (PMID 25051364, 2014). "Furthermore, IGF2BP2 deficiency impaired tumor-associated macrophage (TAM)-like polarization in vitro, as evidenced by decreased expression of TAM markers, such as Mrc1, Mmp2, and Il10." (PMID 41943844, 2026). "The authors also discovered that metastatic tumor cells tend to express the ligand CD47, an important “don’t-eat-me” signal, which may influence the anti-tumor immunity of MRC1+ CCL18+ macrophages via its corresponding receptor SIRPA." (PMID 40191203, 2025). "Similarly, CD206, also known as the mannose receptor C type 1 (MRC1), is predominantly expressed on M2 macrophages and has been linked to tumor-promoting activities such as angiogenesis and metastasis." (PMID 39858472, 2025). "In addition, Pdgfc, which promotes angiogenesis and the immunosuppressive cytokine Interleukin 10 (Il10), that contributes to tumor immune evasion, were upregulated in Mir34aΔMye macrophages, particularly in the Mrc1+ subtype." (PMID 39425000, 2025). "Importantly, the MFP of PyMT-RIDad mice also exhibited an enrichment of immunoregulatory molecules such as Ido1, Mrc1, and Cd200, suggesting a shift toward a generally immunosuppressive tumor microenvironment." (PMID 40526430, 2025). "The PTSO-induced downregulation of MRC1 may therefore enhance tumor immunogenicity, contributing to the observed anti-tumor effects in treated mice." (PMID 41010517, 2025). "Furthermore, spatially co-localized MRC1-expressing resident tissue macrophages (RTM-TAMs) secrete pro-tumor cytokines upon interaction with SLPI+ tumor cells, alongside cancer-associated myofibroblasts (myo-CAFs) exhibiting reduced type I collagen production." (PMID 41216859, 2025). "Interestingly, our findings also indicate that RIDα/β overexpression in adipocytes promotes an immunosuppressive tumor microenvironment through upregulation of Ido1, Mrc1, and Cd200." (PMID 40526430, 2025). "Moreover, the MRC1+ cells were also CD163+, which is expressed by monocytes and macrophages and found on tumor associated macrophages as well as M2 macrophages." (PMID 38532508, 2024). "MRC1+ macrophages facilitate tumour recurrence following chemotherapy, and tumour biopsy samples from cancer patients who received neoadjuvant therapy had a much larger infiltrate of CD45+CD11b+CD14+ macrophages than those from patients who received only surgery." (PMID 38982317, 2024). "Importantly correlation analyses showed significant co-expression between CMKLR1 and genes specific of tumor associated macrophages (TAM) such as CD14, CD163, MRC1 and HLA-DRA in BC and MPM." (PMID 37539056, 2023). "M2‐TAMs are tumor‐promoting macrophages and showed high expression of MRC1, CD163, MARCO, and MAF." (PMID 36529697, 2023). "Since CXCR4 was highly expressed across most T cell subsets in BrM.ICB, the MRC1+LYVE1+ macrophage population could recruit these T cells into the BrM tumor parenchyma through CXCR4:CXCL12 interactions." (PMID 37655659, 2023). "Notably, AMPKα1 deletion reduced the expression of markers of anti-inflammatory M2 macrophages Ym1, Mannose receptor C-type 1 (MRC1), CD36, CD301 and Glutamine synthetase (GS), as well as CD169, a marker for M2-like tumour-associated macrophages." (PMID 36586434, 2023). "Macrophage mannose receptor 1 (MRC1), also known as CD206, affects tumour immunity." (PMID 37965573, 2023). "We then confirmed that MRC1, as a marker of macrophages in metastatic LN, might be used as a target of tumor therapy." (PMID 36569924, 2022). "In this study, we found that C1QA and C1QC were highly expressed in both tumors and metastatic LN, while MRC1 was only highly expressed in metastatic LN, indicating that MRC1 could be used as a marker to predicate tumor metastasis." (PMID 36569924, 2022).